SLIT2 (slit guidance ligand 2)
Diseases named in the same sentence as SLIT2 in open-access papers (continued):
Sharing a sentence is not in itself a finding about the gene and the disease.
cancer (continued). "SLIT2, secreted by endothelial cells, acts as a chemoattractant for ROBO1-expressing cancer cells." (PMID 36942388, 2023). "SLIT2 is the most commonly studied protein among SLIT family and plays diverse roles in the migration of various types of cells, neural formation, angiogenesis and cancer progression." (PMID 36894950, 2023). "Another study confirmed that SLIT2 expression was reduced in PDAC, and showed that restoring SLIT2 inhibited the neural invasion and metastasis of PDAC, suggesting its suppressive role in nerve–cancer interactions." (PMID 36077804, 2022). "Augsten reported that cancer-suppressive CAFs, type I CAFs, do not express αSMA, have the ligand Slit2, and inhibit the tumorigenicity of cancer cells." (PMID 35804329, 2022). "We, therefore, asked if SLIT2 could inhibit macropinocytosis, and therefore the growth of RAS-transformed cancer cells." (PMID 32807784, 2020). "ROBO2 and SLIT2 proteins were highly expressed in normal tissue compared to cancer samples (data not shown)." (PMID 31921388, 2019). "SLIT2 (slit guidance ligand 2) and ROBO1 (roundabout guidance receptor 1) are a ligand and a cognate receptor, respectively, that trigger the signaling that controls axon guidance, neurogenesis and cancer progression." (PMID 31827074, 2019). "All of these malignant tumors are characterized by a lower level of Slit2 expression than is present in non-neoplastic tissue." (PMID 29864155, 2018). "However, SLIT2/ROBO1 has also been correlated with poor prognosis and has reported cancer-promoting properties." (PMID 29523788, 2018). "Whether srGAP1-Cdc42 axis is a key downstream functional target of Slit2 signaling in CRC remains to be elucidated and little was known about the expression and clinical significance of srGAP1 in human cancer." (PMID 27923383, 2016). "Therefore, CAFs-derived SLIT2 increased the expression and phosphorylation levels of CTTN, which induced cytoskeletal reorganization and led to the acquirement of excessive migratory capacities of cancer cells." (PMID 37443302, 2023). "SLIT2 promoted the migration of endothelial cells and promoted the angiogenic activity via the ROBO1-VEGFR2-ERK1/2 signaling pathway; current data showed that the SLIT/ROBO pathway could be a promising therapeutic target for cancer." (PMID 36910471, 2023). "In addition, our model describes the kinetic parameters of fibroblast signaling molecules (SLIT2 and CXCL12) with a polynomial which is dependent on cancer cell signaling factors (LIF and TGFβ); an attitude which is an innovative procedure in agent-based modeling structure." (PMID 32384110, 2020). "Moreover, using the DepMap portal to evaluate the gene dependency dataset (DEMETER scores) from 17 AML cell lines included in the Cancer Cell Line Encyclopedia (CCLE), we observed an increase in cell proliferation for most of the cell lines upon SLIT2 knockdown." (PMID 33120864, 2020). "Thus, the results of our study suggested that the upregulation of Slit2-WT, but not Slit2-ΔE15, in a cancer microenvironment is an important factor in suppressing immunity while not interfering with cancer growth." (PMID 30717252, 2019). "The expression profile of Slit2 shows no clear trend among different cancers." (PMID 25605242, 2015). "Accordingly, generation of two different sets of nonlinear ODEs let us describe cancer cell and fibroblast dynamics and could determine the critical time-points of switching in SLIT2 and CXCL12 genes which are essential for fibroblast status change from normal to cancer associated type." (PMID 32384110, 2020). "Methylation level of DAPK1, SLIT2, WIF1 and RARB genes combined distinguished cancer from normal cervical tissues and had significantly higher specificity compared to HPV detection and age alone." (PMID 25826459, 2015).
infection (8 papers, 2013 to 2025). The state of being infected such as from the introduction of a foreign agent such as serum, vaccine, antigenic substance or organism. "We identified 891 SLIT2 mutation carriers, of whom 426 had at least one infection diagnosis (47.8%)." (PMID 31712607, 2019). "However, further studies and functional work are required to support SLIT2 as a candidate gene for infection, given its only-suggestive association in this study." (PMID 31712607, 2019). "In a murine model of S. aureus skin and soft tissue infection (SSTI), local SLIT2 levels fall initially but increase subsequently, peaking at 3 days after infection." (PMID 37773612, 2023). "Together, our findings suggest that immediately after infection the rapid decrease in local levels of SLIT2 promotes infiltration of neutrophils into the site of infection." (PMID 37773612, 2023). "Infection of HMEC-1 with S. aureus was sufficient to reduce SLIT2 production at 12 hr at the level of mRNA as well as protein." (PMID 37773612, 2023). "SLIT2 and PRUNE2 represent infection-associated genes where expression was assessed as higher by RNA-seq in Holstein relative to Sahiwal infected cells." (PMID 35061738, 2022). "In the present study, we showed that Slit2 not only inhibited infection of T-cells with cell-free virus, but also inhibited cell-cell transmission of HIV-1 using coculture of HIV-1–infected and noninfected cells." (PMID 23294842, 2013). "They as part of a potential compensatory mechanism aimed at preserving vascular integrity during infection-induced vascular stress, since the inflammatory stimuli, triggered by an infection, can downregulate the SLIT2/ROBO4 axis, leading to increased vascular permeability." (PMID 40124360, 2025). "Using a murine model of community-associated S. aureus-induced SSTI, we found that endogenous levels of SLIT2 protein at the site of infection were significantly reduced at 12 hr after infection, and subsequently increased to reach a peak at 3 days post-infection." (PMID 37773612, 2023). "In this manner, spatiotemporal regulation of SLIT2/ROBO1 activity may potently direct bacterial killing and confer effective host protection against pathogenic infection." (PMID 37773612, 2023). "Surprisingly, we found that local SLIT2 levels were reduced as early as 12 hr after the infection." (PMID 37773612, 2023). "Similarly, a number of genes placed in “Axonal guidance”, including several modulated by infection (SLIT2, PLCD1, SLIT-ROBO Rho GTPase-activating protein 2 (SRGAP2) and TUBA4A), showed elevated expression." (PMID 37276213, 2023). "Our results suggest that changes in the levels of SLIT2 at local sites of infection may coordinate neutrophil recruitment, retention, and bactericidal responses to effectively and synergistically target S. aureus." (PMID 37773612, 2023). "Temporal fluctuations in local SLIT2 levels may promote neutrophil recruitment and retention at the infection site and hasten bacterial clearance by augmenting neutrophil oxidative burst and degranulation." (PMID 37773612, 2023). "SLIT2, LITAF, PRUNE2 and genes involved in “Integrin signalling” showed altered numbers of TashAT2 motifs and, together with “PI3K/AKT signalling”, integrin signalling genes were significantly enriched by IPA in the Infection Associated-H/S data set." (PMID 35061738, 2022). "17,928 individuals did not carry a mutation in SLIT2, and 8214 of those had at least one infection diagnosis (45.8%)." (PMID 31712607, 2019).
adenocarcinoma (4 papers, 2020 to 2025). A common cancer characterized by the presence of malignant glandular cells. "In our study, we observed increased expression of SLIT1 and SLIT2 in the Pten model, which develops advanced-stage adenocarcinomas with prominent stromal invasion." (PMID 40508075, 2025).
bacterial infection (3 papers, 2023). "Taken together, these results indicate that host-derived SLIT2 plays an important role in the spatiotemporal modulation of innate immune responses during bacterial infection." (PMID 37773612, 2023). "Further studies are needed to explore the precise mechanisms by which levels of SLIT2 are modulated in the face of bacterial infection and to explore the potential of SLIT2 as a novel anti-microbial therapeutic." (PMID 37773612, 2023). "Conditioned media from HMEC-1 cells taken 48 hr after bacterial infection boosted LL-37 secretion and this effect was blocked by SLIT2 neutralization using N-ROBO1." (PMID 37773612, 2023). "Together, these results suggest that Slit2-N plays a role in defending against bacterial infection and that Slit2-type LRR region-containing proteins might represent a novel type of immune receptor." (PMID 37044216, 2023). "Together, these findings reveal that auto/paracrine SLIT2/ROBO1 signaling in HeLa cells impacts organelle control and innate immune defenses to bacterial infection via repression of mTORC1 under normal growth conditions." (PMID 37311584, 2023). "Interestingly, in the absence of bacterial infection, neutralization of endogenous SLIT2 augmented immune cell infiltration in the skin but did not result in local tissue damage in the form of acanthosis." (PMID 37773612, 2023).
neurodegenerative disease (2 papers, 2022 to 2025). A disorder of the central nervous system characterized by gradual and progressive loss of neural tissue and neurologic function. "Supporting its relevance to neurodegenerative diseases, SLIT2 overexpression in transgenic mice displays increased blood-brain barrier permeability and AD-like neuropathology." (PMID 41331787, 2025).
central nervous system disorder (1 paper, 2024). A disease involving the central nervous system. "Consequently, SLIT2 could potentially be targeted for therapeutic interventions in central nervous system disorders." (PMID 39038036, 2024).
vasculopathy (1 paper, 2012). "Furthermore, we propose that elevated levels of Slit2 may protect the lymphatic channels from HIV-induced vasculopathy and HIV spread." (PMID 22241990, 2012).
SLIT2 also shares sentences with these, for which no sentence is quoted: brain injury (3 papers); endometriosis (3); epilepsy (3); skin cancer (3); colorectal (2); fibrosarcoma (2); invasive breast carcinoma (2); pilocytic astrocytoma (2); renal cell carcinoma (2); acute lymphoblastic leukemia (1); adenomyosis (1); Anisometropia (1); anxiety disorder (1); astrocytomas (1); Autoimmunity (1); bipolar disorder (1); bladder cancer (1); chronic lymphocytic leukemia (1); coeliac disease (1); colon adenocarcinoma (1); coronary heart disease (1); COVID-19 (1); ductal carcinoma in situ (1); dyslexia (1); dysplasia (1); Epiretinal membrane (1); esophageal cancer (1); germinal matrix hemorrhage (1); heart failure (1); Hirschsprung disease (1).
A further 33 diseases each share a sentence with SLIT2 in 1 paper.